MDM2 (MDM2 proto-oncogene)
Diseases named in the same sentence as MDM2 in open-access papers (continued):
Sharing a sentence is not in itself a finding about the gene and the disease.
inflammatory myofibroblastic tumor (7 papers, 2014 to 2025). A multinodular intermediate fibroblastic neoplasm that arises from soft tissue or viscera, in children and young adults. "This case demonstrates that there may also be a role for MDM2 studies to exclude a diagnosis of WDLPS with extreme sclerosis in patients apparently presenting with a retroperitoneal inflammatory pseudotumor." (PMID 26987706, 2016). "Distinguishing between WDLPS with extreme sclerosis and fibrosing inflammatory pseudotumor can be equally problematic, but FISH studies for MDM2 are infrequently used in this setting." (PMID 26987706, 2016). "IgG4-related disease or inflammatory myofibroblastic tumor typically do not have lipoblasts and are not MDM2 positive." (PMID 40290567, 2025).
kidney cancer (7 papers, 2014 to 2023). Primary or metastatic malignant neoplasm involving the kidney.
laryngeal carcinoma (7 papers, 2010 to 2023). Carcinoma that arises from the laryngeal epithelium. "The lowest expression of MDM2 protein was observed in larynx carcinoma specimens." (PMID 36551770, 2022). "MDM2 overexpression protein has also been reported in HNSCC and laryngeal cancer." (PMID 37185737, 2023).
mesenchymal tumors (7 papers, 2015 to 2026). "DDL are aggressive mesenchymal tumors known for their genomic amplification of the MDM2 oncogene." (PMID 40165894, 2025). "MDM2 and CDK4 overexpression are not usually seen in benign tumors but quite common in intermediate or malignant mesenchymal tumors and was diffusely positive in this case." (PMID 26315812, 2015).
ovarian tumor (7 papers, 1996 to 2025). "Interestingly, the mean expression of the three genes (TYMS, ZEB2, and MDM2) was upregulated in all ovarian tumor subtype analyzed." (PMID 30038317, 2018). "This may suggest that in ovarian tumours also, 20q13 and MDM2 amplifications occur in late or aggressive cancers." (PMID 8980401, 1996). "However, the frequency of Mdm2 or Mdm4 overexpression is low (2-4%) in ovarian tumor cells and cancer patients or non-existent in cis-Pt-resistant ovarian tumor cell lines." (PMID 28038466, 2017).
rheumatoid arthritis (7 papers, 2015 to 2025). A chronic, systemic autoimmune disorder characterized by inflammation in the synovial membranes and articular surfaces. "Another study found a potential association between the del1518 variants in MDM2 and rheumatoid arthritis and indicates that combinatorial genotypes and haplotypes in the MDM2 locus may be linked to rheumatoid arthritis." (PMID 37254181, 2023). "The presence of anti-MDM2 still needs to be investigated in other autoimmune diseases such as rheumatoid arthritis, systemic sclerosis, Sjögren's syndrome, and dermatomyositis." (PMID 26090506, 2015).
spindle cell sarcoma (7 papers, 2014 to 2025). A malignant mesenchymal neoplasm composed of spindle-shaped cells. "After extensive immunohistochemical analysis, including antibodies against pan-cytokeratin, S100, CD34, beta-catenin, SMA, desmin, CD10 and MDM2, the tumor was classified as high-grade spindle cell sarcoma NOS." (PMID 35645621, 2022). "In the present study, we describe a spindle cell sarcoma with ring chromosome composed of chromosome 12 material, several fusion genes mapping to 12q, and amplification of MDM2." (PMID 25176350, 2014). "Spindle cell sarcomas usually show positive immunoreactivity for vimentin, osteopontin, and MDM2." (PMID 25888133, 2015). "The immunohistochemical analysis of MDM2, CDK4, and SATB2 in this case report was positive, indicating that this spindle cell sarcoma belongs to the category of bone sarcomas." (PMID 39634267, 2024).
uveal melanoma (7 papers, 2016 to 2026). A melanoma derived from melanocytes of the uveal tract. "Combined with our experimental data, it is rational to conclude that the effect of JMJD2C in CDDP resistance in uveal melanoma cells is promisingly achieved through its upregulation on MDM2." (PMID 35468881, 2022). "The co-inhibited MDM2 with Bcl-2/XL/W has been highlighted to function as a promising target for treatment of uveal melanoma." (PMID 35468881, 2022). "RT-qPCR results demonstrated that the expression of MDM2 was noticeably higher in uveal melanoma tissues than in the normal uveal tissues." (PMID 35468881, 2022). "Next, MUM-2B/CDDP cells were subjected to different treatments to study the effect of JMJD2C on drug resistance of uveal melanoma cells by regulating MDM2." (PMID 35468881, 2022). "We then proceeded to analyze the downstream mechanism of MDM2 participating in the CDDP resistance in uveal melanoma." (PMID 35468881, 2022). "In addition, we found in this study that JMJD2C promoted CDDP resistance in uveal melanoma cells via histone demethylation of the MDM2 promoter." (PMID 35468881, 2022). "Moreover, reduced upregulation of MDM2 dependent on microRNA-17-3p could aid in the prevention against the progression of uveal melanoma." (PMID 35468881, 2022). "Overall, JMJD2C can promote the expression of MDM2 by removing histone methylation of MDM2 promoter, thus promoting CDDP resistance in uveal melanoma cells." (PMID 35468881, 2022).
uveal melanoma (continued). "Here, we analyzed their correlation in uveal melanoma included in TCGA, and demonstrated a significant positive correlation between JMJD2C and MDM2 mRNA expression in uveal melanoma." (PMID 35468881, 2022). "For instance, MDM2 could regulate JMJD6 degradation to diminish H2A.X phosphorylation, thereby resulting in uncontrolled uveal melanoma cell migration." (PMID 35468881, 2022).
acute leukemia (6 papers, 2015 to 2025). A clonal (malignant) hematopoietic disorder with an acute onset, affecting the bone marrow and the peripheral blood. "While efficacy has been limited thus far, several MDM2 inhibitors have been tested in patients with acute leukemia." (PMID 41514580, 2025). "We investigated autophagy induction in acute leukemia by Nutlin 3a, a first-in-class MDM2 inhibitor." (PMID 26440941, 2015). "Our observation that inhibition of ATM or MDM2 sensitizes acute leukemia cells to CLM may provide the rationale for the clinical exploration of a combination therapy with either GO or InO." (PMID 41514580, 2025).
anemia (6 papers, 2013 to 2024). A reduction in the number of red blood cells, the amount of hemoglobin, and/or the volume of packed red blood cells.
astrocytomas (6 papers, 1997 to 2025). "Consistent with parent recurrent tumor cells, amplifications of CDK4 and MDM2 and PDGFRA gain were found, while CDKN2A/B was identified as homozygous deletion in the xenografts, qualifying for integrated diagnosis of astrocytoma, IDH2-mutant, CNS WHO grade 4." (PMID 38012788, 2023). "Consistent with YMG25R parent tumor cells, gain of PDGFRA and amplification of CDK4 and MDM2 were observed, while CDKN2A HD was identified in the xenografts, qualifying for astrocytoma, IDH-mutant, CNS WHO grade 4 according to the WHO CNS5 criteria." (PMID 38012788, 2023). "To verify if IDH1/2-mutant astrocytomas with CDKN2A, PDGFRA, CDK4, or MDM2 CNA promotes poor prognosis, we used the GLASS and MSK diffuse glioma datasets (total 1,448 cases)." (PMID 38012788, 2023). "V12Ha-Ras transgenic mice under the control of the GFAP promoter form astrocytomas that have the added genetic complexity of the aberrant expression of p16, p19, and PTEN while overexpressing EGFR, MDM2, and CDK4, with chromosomal rearrangements comparable to human astrocytomas." (PMID 41154198, 2025). "In IDH1-mutant astrocytoma cases with available clinical and CNA data (total 161 cases), we found that tumors harboring either CDKN2A deletion, PDGFRA amplification, CDK4 amplification, or MDM2 amplification conferred poor prognosis in these cohorts." (PMID 38012788, 2023).
cardiac sarcoma (6 papers, 2019 to 2024). "This adds to the sample-focused analysis of twenty-three cases amid latest 39 months, according to our methods of research in addition to re-do MDM2 profiling in another 35 patients across two studies and another cohort evaluating the outcome in cardiac sarcomas." (PMID 38732333, 2024). "In addition, one single-centric study based on 25 years of data (between January 1993 and June 2018) analysed heart sarcomas and provided a supplementary immunohistochemistry report for the MDM2 profile as the main feature for the intimal type." (PMID 38732333, 2024). "We reviewed the primary cardiac sarcoma cases between January 1993 and June 2018 at Asan Medical Center, South Korea, with their clinicopathologic findings, and reclassified the subtypes, especially using IHC for MDM2 and then, analyzed the significance of prognosis." (PMID 37395142, 2023). "Immunohistochemistry of IS shows positive MDM2 expression, but MDM2 is eventually overexpressed and amplified by fluorescence in situ hybridization (FISH), quantitative PCR (qPCR) or array comparative genomic hybridization (CGH) to distinguish IS and other cardiac sarcoma tissue subtypes." (PMID 38835391, 2024).
clear-cell renal cell carcinoma (6 papers, 2010 to 2020). "This may act to counter the proliferative effects of MYC, cyclin D1 and MDM2; however, and concerningly, CDKN1A is also overexpressed in clear-cell renal cell carcinoma relative to normal kidney." (PMID 24827579, 2014).
gastrointestinal stromal tumor (6 papers, 2018 to 2025). "Some examples include EWSR1 gene rearrangement in Ewing sarcoma, MDM2 gene amplification in well-differentiated and dedifferentiated liposarcoma, and c-KIT gene mutations in gastrointestinal stromal tumor (GIST)." (PMID 33802620, 2021).
glomerulosclerosis (6 papers, 2017 to 2025). A hardening of the kidney glomerulus caused by scarring of the blood vessels. "METTL3 knockout inhibited the abnormal activation of the MDM2‐Notch1 pathway, preventing podocyte death during the initial phases of glomerular injury and alleviating glomerulosclerosis." (PMID 40421968, 2025). "However UA administration can regulate P62-mediated autophagy flux and sequentially inhibit the abnormal activation of the MDM2-Notch1 pathway, preventing podocyte death during the initial phases of glomerular injury and thus alleviating glomerulosclerosis." (PMID 38993555, 2024). "Targeting METTL3 may prevent MDM2-Notch1 mediated podocyte injury and glomerulosclerosis in DKD." (PMID 41009556, 2025). "Complete MDM2 knockout in vivo may result in proteinuria and glomerulosclerosis." (PMID 28643424, 2017). "Indeed, inhibiting MDM2 by genetic strategy confirmed the pivotal role of MDM2 in mediating high glucose-induced cell proliferation and ECM accumulation in GMCs, which are two crucial events leading to glomerulosclerosis in DKD." (PMID 28871126, 2017).
gynecological cancers (6 papers, 2015 to 2023). "Adding to this, a second P2-promoter SNP, MDM2 SNP285C, lowers Sp1 binding and essentially counteracts the increased affinity of SP1 for the MDM2 SNP309G, located 24 base pairs downstream (as reported in female reproductive cancers)." (PMID 33664771, 2021).
head and neck squamous cell carcinoma (6 papers, 2011 to 2023). A squamous cell carcinoma that arises from any of the following anatomic sites: lip and oral cavity, nasal cavity, paranasal sinuses, pharynx, larynx, and salivary glands. "Again, our findings are in agreement with another study on head and neck squamous cell carcinomas, showing that proliferative lymphocytes are vulnerable to MDM2 inhibition." (PMID 37894319, 2023). "Another study also showed that MDM2 SNP309 G allele probably acts as an important head and neck squamous cell carcinoma (HNSCC) protective factor in Caucasians, but not in Asians." (PMID 23383041, 2013).